PRL (prolactin)
Diseases named in the same sentence as PRL in open-access papers (continued):
Sharing a sentence is not in itself a finding about the gene and the disease.
Anxiety (continued). "For the pituitary hormone prolactin, which exhibits anxiolytic and stress-relieving properties, a negative association between serum levels and anxiety scores in nursing mothers has been found." (PMID 32296356, 2020). "However, in our study prolactin correlated negatively with depression and anxiety in mothers of preterm infants." (PMID 32296356, 2020). "To sum up, we summarized psychosocial factors (including alexithymia, depression, anxiety, negative emotions, perceived stress) and sex hormones (including estrogens, progesterone, androgens, PRL) affecting the susceptibility and development of SLE." (PMID 31275761, 2019). "Interestingly, chronic stress induces similar atrophy of distal PrL pyramidal neuron apical trees, and enhanced stress and anxiety are characteristic symptoms reported by humans using and withdrawing from cannabis." (PMID 30283037, 2019). "Reduced anxiety via the OXT system under high-PRL might reduce threat-related thoughts, which could extend the Nogo-N2 latency." (PMID 31101072, 2019). "Indeed, reduction of PRL levels during early pregnancy affects olfactory bulb neurogenesis and increases postpartum anxiety in the female rat." (PMID 27065946, 2016). "Changes in neurotransmission during lactation of other neuromodulators that can alter indices of anxiety, such as oxytocin, prolactin, or GABA, may have helped remove or mask the normal differences in anxiety between the genotypes in this study." (PMID 17331244, 2007). "Previous work investigating the functional consequences of prolactin‐induced SVZ mitogenesis showed that blocking prolactin secretion using the dopamine D2 agonist bromocriptine during early pregnancy caused consequential deficits in maternal care and increased anxiety‐like behavior post‐partum." (PMID 40457890, 2025). "Prenatal anxiety symptoms might also influence the hormonal balance of oxytocin, vasopressin, prolactin, and the sex hormones estradiol, progesterone, and testosterone which have been associated with influencing the onset and maintenance of maternal and paternal behavior." (PMID 40926200, 2025). "The outcomes included efficacy (changes in depression, anxiety, clinical global impression, disability and quality of life), acceptability (dropout, manic switch, suicidality and side effects) and metabolic/endocrine profiles (changes in body weight, glucose, lipid and prolactin levels)." (PMID 39557452, 2024). "Additionally, this study investigated the correlations between anxiety, depression, sleep disturbances, self-efficacy, and PRL levels in prolactinoma patients, thus providing evidence for targeted interventions to improve the quality of life and psychological status of prolactinoma patients." (PMID 38572480, 2024). "Injecting OXT into the PrL could eliminate anxiety‐like and social resistance behaviors." (PMID 39295107, 2024). "Second, this was a single-center retrospective study, and future research could include multicenter prospective studies to further investigate the relationships and mechanisms between PRL levels and both prolactinoma and sleep disorders as well as the severity of anxiety." (PMID 38572480, 2024). "Thus, the attenuation of the left PrL inhibition-induced anxiogenesis produced by injection of AP7 into the right PrL suggests that the NMDA glutamate receptor located in the RmPFC plays an important role in the mediation of anxiety responses." (PMID 34497496, 2021). "Therefore, we tested the hypothesis that microinjection of OT into the PrL restores the anxiety-like behavior and social preference that were altered by preweaning PD." (PMID 31084703, 2019). "However, decreased maternal serum levels of prolactin have been reported in human mothers with postnatal depression symptoms and increased levels in mothers with low anxiety scores during pregnancy." (PMID 27523184, 2016). "Moreover, PRL modulates anxiety and depressive-like behaviors." (PMID 27065946, 2016).
Anxiety (continued). "In this retrospective study, we analyzed the relationship between prolactin (PRL) levels in patients with prolactinoma and anxiety, self-efficacy, and sleep." (PMID 38572480, 2024). "The synaptic connections between PrL layer II/III pyramidal neurons and other brain areas are important for social behavior, communication, cognition and anxiety." (PMID 38503925, 2024). "Anxiety-like responses, anhedonia, and despair-like behavioral tests were also performed to assess the antidepressant-like effects of HFS PrL." (PMID 37296570, 2023). "Firstly, TNF-α signaling and its protein level were increased in the PrL, and TNF-α expression positively correlated with anxiety level in both sham and SNI mice." (PMID 36917193, 2023). "In this case-control study, researchers emphasized BMI, stress, anxiety, depression, and serum levels of LH, FSH, prolactin, TSH, free T4, estradiol, and testosterone to find an association with secondary amenorrhea among the medical students of UMS." (PMID 38022313, 2023). "In turn, optical inhibition of the PrL-l/vlPAG circuit decreased the pain threshold in both SNI and sham mice, whereas it showed little effect on anxiety-like behaviors." (PMID 36917193, 2023). "In our study, 17 core common targets of ACG and anxiety were predicted, of which ESR1, SRC, AKT1, MAPK8, EGFR, and MMP9 belong to the prolactin and estrogen signaling pathways." (PMID 35624976, 2022). "Chronic administration of prolactin for 5 days in virgin rats reduces ACTH and corticosterone secretion following a restraint or anxiety-like stressor." (PMID 34927138, 2021). "Injection of highly specific OTA into the PrL region of the mPFC increases anxiety-like behavior in postpartum females, and OTR blockade in the postpartum PrL impairs maternal care behavior and enhances maternal aggression." (PMID 31084703, 2019). "In the anxiety-promoting DR projection sites (BLA, PrL, IL), post hoc analysis revealed stress increased 5-HIAA content in Fgf8 HET mice but not WT mice (p = 0.017, p = 0.010, and p = 0.001, respectively)." (PMID 24992493, 2014). "In addition, PRL administration induced a reduction in ACTH and corticosterone secretion in virgin rats exposed to anxiety-like stressors." (PMID 41009573, 2025). "Compared to patients with severe anxiety, those without anxiety (P < 0.001) and those with mild anxiety (P < 0.001) had lower PRL levels." (PMID 38572480, 2024). "PRL levels in patients with prolactinoma are related to education level, tumor size, number of visits, anxiety, self-efficacy, and sleep but not depression." (PMID 38572480, 2024). "An elevated prolactin (PRL) and malfunction of the hypothalamic-pituitary-ovarian (HPO) axis could result from a recent mental condition, such as depression, anxiety, or sleeplessness, which was reported by 36 of the 75 patients (48%) in a previous study." (PMID 38738039, 2024). "The GEE model showed that the anxiety group and the nonanxiety group had significantly different PRL levels at each time point (P < 0.001)." (PMID 38572480, 2024). "The difference in PRL levels between patients with moderate anxiety (P = 0.054) and patients with severe anxiety was not statistically significant." (PMID 38572480, 2024). "Our results showed that PRL levels in prolactinoma patients were related to anxiety, self-efficacy, and sleep but not depression." (PMID 38572480, 2024). "GEE single-effect analysis was used to compare PRL levels at different time points between anxiety group and nonanxiety group, between insomnia group and normal group, and between low, medium, and high self-efficacy groups." (PMID 38572480, 2024). "The PrL-BLA circuit was activated by blue laser lights, and the pain threshold and anxiety-like behaviors were examined 1 week after SNI surgery when the mice hadn’t displayed anxiety-like phenotypes." (PMID 36917193, 2023). "Optogenetic manipulations of the PrL-BLA circuit modulate anxiety-like behaviors but not hyperalgesia in mice with chronic pain." (PMID 36917193, 2023).
Anxiety (continued). "In contrast, the injection of an NTS1 antagonist into the PrL had no anxiety-like effect on normal rats but reduced the anxiogenic stress-related effects." (PMID 36829752, 2023). "Secondly, direct infusion of TNF-α into the PrL induced anxiety-like behaviors without influencing the pain threshold." (PMID 36917193, 2023). "Interestingly, VTA-lesioned sham animals had increased anxiety and forced swim immobility, which was reversed by HFS PrL." (PMID 37296570, 2023). "The PrL-l/vlPAG circuit is required for modulation of pain perception but not anxiety-like behaviors." (PMID 36917193, 2023). "Together, these data suggest that the PrL-PAG circuit is vital for regulating pain perception but not anxiety-like behaviors in mice with chronic pain." (PMID 36917193, 2023). "A study using another animal model of depression known as conditioned stress showed that fluoxetine, which is a selective serotonin reuptake inhibitor, reversed stress- and anxiety-related effects but did not reduce high PRL levels induced by stress." (PMID 36833950, 2023). "Together, these results demonstrate a pivotal role of the PrL-BLA circuit in regulating anxiety-like behaviors but not hyperalgesia in mice with chronic pain." (PMID 36917193, 2023). "To examine whether TNF-α in the PrL plays a role in pain perception or anxiety-like behaviors, we injected recombinant TNF-α protein directly into the PrL region of WT mice." (PMID 36917193, 2023). "The infusion of mTOR-siRNAs in the PrL cortex did not produce changes in any of the tests used to evaluate depressive- or anxiety-like behaviors." (PMID 34445375, 2021). "As a consequence, a clear anxiogenic-like effect was observed with CoCl2 injection into the left PrL, but not into the Cg1, suggesting a marked role of this subarea in the modulation of anxiety." (PMID 34497496, 2021). "A previous study reported a negative correlation between anxiety and prolactin in women giving birth at full term." (PMID 32296356, 2020). "We speculate that OT might regulate anxiety-like behavior and social preference in males via OTR and V1aR in the PrL." (PMID 31084703, 2019). "This would imply a non-dimorphic regulatory role of PRL on the stress response (in addition to its dimorphic role on anxiety), which requires further research." (PMID 30571750, 2018). "When postpartum women have no anxiety and stress, prolactin levels will be increased and breastfeeding outcomes will be improved." (PMID 29114266, 2017). "For example, infusion of ovine PRL into the lateral cerebral ventricle produces anxiolytic effects, whereas down-regulation of PRLR following treatment with antisense oligonucleotide produces elevated anxiety- like behaviors." (PMID 27893788, 2016). "For example, animal phobics reported a strong increase in subjective anxiety after forced exposure, without accompanying changes in prolactin levels." (PMID 27504102, 2016). "However, significant differences did emerge in the MSL of the MWT (p < 0.001), in state anxiety levels (p = 0.009), IPI scores (p = 0.002), DSST scores (p = 0.013), SST scores (p = 0.003) and levels of PRL (p = 0.003) and TSH (p = 0.003)." (PMID 25091387, 2014). "Given the fact that both OXT and PRL are key players during the peripartum period, acting synergistically to regulate maternal care, anxiety, and stress, it is not surprising PRL-R expression is comparably altered during that time." (PMID 24883213, 2014). "Hence, this study investigated the hypothesis that prolactin‐induced Igf2 expression in CP tissue during pregnancy and lactation is required for increases in SVZ mitogenesis necessary to alleviate post‐partum anxiety/depression." (PMID 40457890, 2025). "Notably, behavioral assays revealed that in mice with ISDN-induced chronic headache and anxiety comorbidity, systemic CNO-evoked chemogenetic inhibition of PrL-projecting vAI neurons attenuated cephalic cutaneous allodynia without altering anxiety-like behaviors in the OFT or EPM tests." (PMID 41377021, 2025).
Anxiety (continued). "Comparison of PRL between the anxiety and nonanxiety groups." (PMID 38572480, 2024). "Using optogenetic manipulations, we demonstrate that the PrL-BLA and PrL-l/vlPAG circuits individually mediate anxiety-like behaviors and hyperalgesia in chronic pain, offering what we believe to be a new line of evidence to support the divergent-pathway-centered hypothesis." (PMID 36917193, 2023). "Because negative emotions and anxiety during the feeding of the child may affect the function of the mother's cerebral cortex, hypothalamus, and pituitary gland, reduce the secretion of prolactin and oxytocin and finally reduce the breast milk secretion." (PMID 37452292, 2023). "However, we found that stimulation of the PrL neuronal terminal in the l/vlPAG only induced an analgesic effect without influencing anxiety-like behaviors." (PMID 36917193, 2023). "To test whether TNFR1 mediated the effects of TNF-α on chronic pain-induced anxiety, we knocked down Tnfr1 specifically in PrLBLA neurons with an injection of retrograde AAV-Cre virus into the BLA and AAV-DIO-Tnfr1-shRNA-eGFP into the PrL." (PMID 36917193, 2023). "It is noteworthy that optogenetic activation of the PrL-BLA circuit in early SNI mice but not in sham mice significantly induced anxiety-like behaviors, suggesting that the effect of the PrL-BLA circuit on anxiety-like behaviors may be context dependent." (PMID 36917193, 2023). "PRL may change in response to psychological stress also in humans, where different studies have shown a positive correlation between anxiety and negative emotions and serum PRL." (PMID 34573561, 2021). "Burnout subjects in prolactin profile had high scores on depression, but burnout subjects showing low prolactin levels were characterized by low attachment/high distance, and more severe state negative affect and anxiety." (PMID 33322399, 2020). "Long-term anxiety, nervousness and other negative emotions can increase catecholamines and PRL in the blood, which may affect ovulation." (PMID 31626086, 2019). "One exception in the current study is represented by dog 1, with high plasmatic prolactin values, probably due to its behavioral problems since it showed a phobia of numerous stimuli, and possibly a state of anxiety (not assessed as it was out if the scope of this study)." (PMID 31277511, 2019). "Interestingly, the limited studies have shown negative impact of raised prolactin on a range of neurocognitive domains encompassing memory and executive function, anxiety and depressive behaviour as well as in regulation of stress responses." (PMID 31253144, 2019). "Psychological conditions, like anxiety and depression, which may cause the fluctuation of TSH, prolactin and TNF-α, were not assessed in the current study." (PMID 25558907, 2014). "Moreover, immunostaining results showed robust c-fos expression in both PrL- and ovBNST-projecting AI neurons after ISDN injection, suggesting that activated PrL- and ovBNST-projecting AI neurons appeared to be involved in chronic headache and comorbid anxiety." (PMID 41377021, 2025). "Moreover, localized CB1 receptor antagonism in PrL and ovBNST respectively reversed JZL184’s analgesic and anxiolytic effects, further establishing the indispensable, differential roles of vAI-PrL and dAI-ovBNST circuits in regulating cephalalgic hyperalgesia and anxiety-like behaviors." (PMID 41377021, 2025). "Furthermore, the secretion of prolactin and estrogen, and interfering with mitogen‐activated protein kinase (MAPK) and tumor necrosis factor (TNF) signaling pathways were mainly involved in the multi‐target therapeutic effects of ZZCD against anxiety and depression." (PMID 37905694, 2024). "However, it might be the case that in males, exclusively activating IL, and not PrL, PV+ neurons, is necessary to heighten stress-induced anxiety, as suggested by the PV/FosB data indicating that only IL PV neurons are impacted by 8 weeks of UCMS." (PMID 36808099, 2023).
Anxiety (continued). "Furthermore, prolactin seems to reduce anxiety-related behavior in both female and male rats, maybe because prolactin acts as an endogenous anxiolytic, both in males and non-pregnant female rats." (PMID 31277511, 2019). "Besides the pathways affected by PRL to regulate anxiety are not yet known, and whether the PRL effects on hippocampal neurogenesis contribute to modulate anxiety is still uncertain." (PMID 27065946, 2016). "Additionally, the regionally selective blockade of IDO by 1-MT either in the PrL or IL failed to produce an anxiolytic effect, suggesting that anxiety-like behaviors that are induced by ICV-STZ might not be attributable to IDO activation in the PrL and IL, which needs further confirmation." (PMID 39000602, 2024). "↓ HbA1C, ovary mass, stress, anxiety and depression (HADS),↔ weight, Prolactin, FSH, LH, AMH, TT,No adverse events occurred." (PMID 38818503, 2024). "Angelo found an improvement in craving, and symptoms of anxiety and depression; however, he did not observe a significant alteration in the levels of ACTH, prolactin, or cortisol." (PMID 37510495, 2023). "Participants who worked two night shifts were better able to maintain wakefulness, had higher anxiety scale scores, poorer initial performance and lack of learning effect on VAT, and higher prolactin levels compared with those who worked four night shifts." (PMID 25091387, 2014). "In comparison with vehicle-injected mice, ISDN-injected mice showed a remarkable elevation of eCB release of vAI neuronal projections in PrL during the Von Frey test but not in the EPM test, suggesting that the eCB of vAI-PrL circuit is likely involved in headache rather than anxiety." (PMID 41377021, 2025). "Moreover, synaptic inhibition of the left PrL or NMDA blockade of the right PrL did not change the frequency of closed-arm entries, a widely used measure of general activity, suggesting that the drug effects were selective on anxiety indices." (PMID 34497496, 2021).